NFAT5 (nuclear factor of activated T cells 5)
Diseases named in the same sentence as NFAT5 in open-access papers (continued):
Sharing a sentence is not in itself a finding about the gene and the disease.
osteoarthritis (4 papers, 2017 to 2021). A noninflammatory degenerative joint disease occurring chiefly in older persons, characterized by degeneration of the articular cartilage, hypertrophy of bone at the margins and changes in the synovial membrane. "Chronic arthritis and inflammation are suppressed by inhibition of NFAT5, while melatonin inhibits sirtuin-1-dependent nicotinamide phosphoribosyltransferase (NAMPT) and NFAT5 signaling in chondrocytes to attenuate osteoarthritis." (PMID 33806698, 2021).
Renal atrophy (4 papers, 2011 to 2025). Atrophy of the kidney. "Mice homozygous for loss of NFAT5 display renal atrophy, but the product of this gene is not calcium-regulated." (PMID 21295565, 2011). "These functional findings align with NFAT5’s established role in renal osmoadaptation, as evidenced by studies showing that mice lacking NFAT5 develop severe renal atrophy and die shortly after birth." (PMID 41584586, 2025).
renal fibrosis (4 papers, 2021 to 2025). A final common manifestation of a wide variety of chronic kidney diseases characterized by glomerulosclerosis and tubulointerstitial fibrosis. "It was further indicated that inhibition of NFAT5 reversed the pathological conditions such as renal fibrosis caused by oe‐lnc‐ISG20." (PMID 33939247, 2021). "The effect of lnc‐ISG20 and miR‐486/NFAT5/p‐AKT axis on DN‐associated renal fibrosis was also verified by means of rescue experiments." (PMID 33939247, 2021). "In both Nfat5 knockout models, we observed massive changes in gene expression pattern, with heightened inflammatory responses and renal injury, culminating in renal fibrosis." (PMID 39874047, 2025). "Based on all above findings, our study indicates towards the existence of a regulatory axis in the pathophysiology of DN, wherein lnc‐ISG20 promotes renal fibrosis via the miR‐486‐5p/NFAT5/p‐AKT pathway." (PMID 33939247, 2021). "Accordingly, we found that lnc‐ISG20 promoted renal fibrosis in DN through impairing miR‐486‐5p‐dependent inhibition of NFAT5 and activating AKT." (PMID 33939247, 2021). "In our study, NFAT5 was found to enhance renal fibrosis via inducing AKT phosphorylation, which deepens our understanding of the molecular mechanisms underlying DN." (PMID 33939247, 2021). "Our collective findings indicate that lnc‐ISG20 promotes the renal fibrosis process in DN by activating AKT through the miR‐486‐5p/NFAT5 axis." (PMID 33939247, 2021). "They concluded that NFAT5 might play critical pathophysiological roles in renal fibrosis by modulating innate and adaptive immune responses." (PMID 39874047, 2025). "Here, these results provide evidence for that lnc‐ISG20 could promote the renal fibrosis in DN via miR‐486‐5p/NFAT5/AKT." (PMID 33939247, 2021). "Hence, these findings indicated that lnc‐ISG20 stimulated AKT phosphorylation and promoted renal fibrosis in DN mice by inducing NFAT5." (PMID 33939247, 2021). "In this study, our data revealed that knockdown of lnc‐ISG20 could inhibit the renal fibrosis of DN, and lnc‐ISG20 could inhibit the expression of miR‐486‐5p which was further found to be able to inhibit the AKT phosphorylation via NFAT5." (PMID 33939247, 2021).
chronic lymphocytic leukemia (3 papers, 2022 to 2025). "NFAT5 expression is elevated in chronic lymphocytic leukaemia (CLL), promoting proliferation and resistance to apoptosis." (PMID 40421201, 2025).
cocaine dependence (3 papers, 2015 to 2018). A psychologically and socially impaired state, with or without physiological changes, that develops as a result of using cocaine and which leads to compulsive behaviors to acquire the substance. "This study highlighted associations between cocaine dependence and five SNPs predicted to alter microRNA binding at the 3′-untranslated region of the NFAT5 gene." (PMID 26506053, 2015). "The results of our experimental design pointed at NFAT5, which is upregulated by cocaine and bears functional risk variants for cocaine dependence." (PMID 26506053, 2015). "The risk allele for cocaine dependence, rs1437134G, determined a decreased NFAT5 expression, an effect that was more pronounced in the presence of the microRNA hsa-miR-509 in the two cell lines tested." (PMID 26506053, 2015). "It is thus tempting to speculate that genetic variants impacting NFAT5 will cause an effect on the expression of relevant downstream genes and on DA activity, which could eventually contribute to cocaine dependence phenotypes." (PMID 26506053, 2015). "Our case–control association study with common genetic variants pointed to five SNPs in NFAT5 as risk factors for cocaine dependence, with rs1437134 surviving the Bonferroni correction for multiple testing and showing evidence of functional effects on gene expression." (PMID 26506053, 2015). "The single-marker analysis showed that five SNPs in the 3′-untranslated region of the NFAT5 gene were associated with cocaine dependence, and two of them (rs1437134 and rs7359336, in high linkage disequilibrium) survived the Bonferroni correction for multiple testing." (PMID 26506053, 2015). "However, further genetic and functional studies of NFAT5 are needed to confirm its role in cocaine dependence." (PMID 26506053, 2015). "Additional evidence suggests that a common functional variant in one of the genes showing increased expression after cocaine exposure, rs1437134 in NFAT5, may contribute to cocaine dependence." (PMID 26506053, 2015).
colitis (3 papers, 2019 to 2025). Inflammation of the colon. "Next, we examined the effect of Nfat5 deficiency and gut microbes on intestinal barrier function to understand the mechanisms underlying Nfat5- and microbiota-mediated protection against colitis." (PMID 40663408, 2025). "In this study, we demonstrate that NFAT5 was required for the survival and proliferation of IECs and that its deficiency accelerated experimental colitis in mice." (PMID 40663408, 2025). "NFAT5 deficiency unveils a 2-pronged mechanism of colitis susceptibility: an epithelium-intrinsic vulnerability to injury and an extrinsic shift in the microbiota toward a colitogenic profile." (PMID 40663408, 2025). "Collectively, these results demonstrate that Nfat5 deficiency played a crucial role in the development of IL-10–dependent spontaneous colitis." (PMID 40663408, 2025). "As expected, we noted more severe colitis symptoms in Nfat5-deficient mice than in their control littermates when they were housed separately." (PMID 40663408, 2025). "Collectively, the comparison of data between separately housed and cohoused mice suggests that gut microbiota is necessary for protection against DSS-induced colitis aggravated by Nfat5 deficiency." (PMID 40663408, 2025). "In addition to distinct microbiome differences associated with NFAT5 expression, our findings from separate housing and cohousing experiments suggest that the gut microbiota influenced colitis severity in Nfat5-deficient mice." (PMID 40663408, 2025). "Here, we demonstrate that NFAT5 was critical for the survival and proliferation of intestinal epithelial cells (IECs) and that its deficiency accelerated chemically induced or spontaneous colitis in mice." (PMID 40663408, 2025). "These intrinsic characteristics associated with NFAT5 deficiency may partially underlie the increased susceptibility to chemically induced or spontaneous colitis observed in Nfat5-deficient mice." (PMID 40663408, 2025). "To determine the role of the gut microbiota in the deterioration of colitis in Nfat5-deficient mice, we first compared the severity of DSS-induced colitis by evaluating weight loss and the DAI score for mice that were either housed separately or cohoused for more than 6 weeks." (PMID 40663408, 2025). "Furthermore, we could not identify any culturable bacteria at the species level and therefore failed to pinpoint specific pathobionts that are directly responsible for exacerbating colitis in the context of Nfat5 deficiency." (PMID 40663408, 2025). "In summary, our research provides insights into the alleviation of experimental colitis by NFAT5 via IEC HSP70, a process that safeguards stem cells and maintains intestinal barrier integrity against inflammation-induced injury." (PMID 40663408, 2025). "Together, these results suggest that NFAT5 contributed to protection against the progression of experimental colitis." (PMID 40663408, 2025). "HSP70 promotes the survival and proliferation of IECs and protects against DSS-induced colitis as an NFAT5 target gene." (PMID 40663408, 2025). "On the basis of our volcano plot analysis and previous reports, we postulated that HSP70 primarily mediates the NFAT5-dependent survival, proliferation, and regenerative capacity of IECs and the progression of colitis." (PMID 40663408, 2025). "Epithelial NFAT5 levels and the gut microbiota contribute to the development of spontaneous colitis in mice." (PMID 40663408, 2025). "Nfat5 knockdown consistently led to a marked loss of proliferating epithelial cells and mucus-producing cells in mice with DSS-induced colitis, as determined by Ki-67 and Alcian blue staining, respectively." (PMID 40663408, 2025). "This study is the first to our knowledge to demonstrate that the protective role of NFAT5 in colitis is mediated via its function in IECs." (PMID 40663408, 2025). "To further determine the role of epithelial NFAT5 in spontaneous colitis, we generated conditional-KO Il10–/–Nfat5IEC-KO and their Il10–/–Nfat5fl/fl mice." (PMID 40663408, 2025).
colitis (continued). "In summary, these findings demonstrate that Nfat5 deficiency altered the gut microbiota, presumably contributing to intestinal barrier dysfunction and increased susceptibility to DSS-induced colitis." (PMID 40663408, 2025). "As expected, these mice, with conditional deletion of Nfat5 in the IECs exhibited more severe colitis with higher DAI and histological scores and rectal prolapse." (PMID 40663408, 2025). "In support of this notion, when transplanted into either WT or Nfat5+/– recipients, feces of Nfat5+/– mice were more effective at inducing DSS colitis than were feces from WT mice." (PMID 40663408, 2025). "NFAT5 regulates epithelial regenerative capacity related to gut homeostasis and microbial composition, preventing colitis progression via HSP70." (PMID 40663408, 2025). "In summary, these data suggest that, as a direct target molecule of NFAT5, HSP70 mediated the NFAT5-dependent survival, proliferation, and regenerative capacity of IECs, consequently preventing the progression of experimental colitis." (PMID 40663408, 2025). "Loss- and gain-of-function experiments involving HSP70 revealed that NFAT5 mitigated experimental colitis through IEC Hsp70, which protected stem cells from inflammation-induced injury and maintained barrier function." (PMID 40663408, 2025). "Together, these observations suggest that both the gut microbiota and the integrity of IECs, compromised by Nfat5 deficiency, contribute to the progression of DSS-induced colitis." (PMID 40663408, 2025). "To this end, we used dextran sulfate sodium (DSS) to induce colitis in Nfat5-haploinsufficient (Nfat5+/–) mice and their WT (Nfat5+/+) littermates." (PMID 40663408, 2025). "Moreover, FMT experiments under antibiotic-driven, germ-free conditions clearly demonstrated that gut microbiota, compromised by Nfat5 deficiency, directly contributed to the progression of DSS-induced colitis." (PMID 40663408, 2025). "After separate housing in addition to distinct microbiome differences associated with NFAT5 expression, our findings from separate housing and cohousing experiments using FMT from Nfat5+/– mice into Nfat5+/– mice resulted in higher colitis severity than that observed in WT (Nfat5+/+) mice." (PMID 40663408, 2025). "Mechanistically, NFAT5 promoted the survival of IECs and the renewal of intestinal stem cells, thereby regulating the production of mucus and antimicrobial compounds, including RegIII and lysozyme, which consequently shape the gut microbial composition to prevent colitis." (PMID 40663408, 2025). "Importantly, these differences disappeared when the mice were cohoused, which concurs with the cohousing data observed in the DSS-induced colitis model, suggesting that the gut microbiota is critical for NFAT5-dependent protection against inflammatory colitis in this spontaneous model as well." (PMID 40663408, 2025). "This association appeared to stem from mechanisms involving the dysregulated NFAT5/HSP70 axis and changes in the gut microbiota, similar to those observed in DSS-induced colitis." (PMID 40663408, 2025). "This supports notion that the NFAT5 expression level in the host (recipients), which originates from genetic differences, determines the development of DSS-induced colitis." (PMID 40663408, 2025). "Both epithelial NFAT5 levels and gut microbiota influence the progression of DSS-induced colitis." (PMID 40663408, 2025). "Moreover, as a key target gene of NFAT5, heat shock protein 70 (HSP70) mediates the survival and proliferation of IECs and protects against colitis." (PMID 40663408, 2025). "Next, to clarify the role of NFAT5 in IECs during DSS-induced colitis, we generated conditional-KO mice lacking Nfat5 specifically in IECs using the Cre/loxP system." (PMID 40663408, 2025). "Mice lacking NFAT5 specifically in T cells exhibited worsened intestinal pathology in an experimental colitis model, coupled with increased interferon gamma (IFNγ) messenger RNA (mRNA) in draining lymph nodes and colon." (PMID 37287987, 2023).
colitis (continued). "Nfat5+/– mice with specific overexpression of Hsp70 in IECs (Hsp70IEC-TGNfat5+/–) had less severe colitis than did Nfat5+/– mice without Hsp70 overexpression (Hsp70WT Nfat5+/–), demonstrating that epithelial HSP70 contributed to the attenuation of DSS-induced colitis accelerated by Nfat5 deficiency." (PMID 40663408, 2025).
colorectal cancer (3 papers, 2021 to 2023). A primary or metastatic malignant neoplasm that affects the colon or rectum. "NFAT5, a transcription regulator, regulates the Wnt/β-catenin signaling pathway and also influences the S100A4 gene, which is a direct transcriptional target of the Wnt/β-catenin/TCF-mediated signaling pathway in colorectal cancer." (PMID 34830168, 2021).
dry eye syndrome (3 papers, 2016 to 2023). A syndrome characterized by dryness of the cornea and conjunctiva. "Previous reports have revealed the associations between the pathogenesis of ocular damage in dry eye syndrome and cataracts and NFAT5 expression." (PMID 31766286, 2019). "Using our cellular model, we also confirmed the activation and involvement of NFAT5 in dry eye sterile inflammation." (PMID 37446230, 2023). "NFAT5 expression and its dependent signaling pathways were deeply related to radiation-induced dry eye, and the condition was improved by ALA treatment." (PMID 31766286, 2019). "Hyperosmolar stress is a key factor of dry eye syndrome, and NFAT5 has been shown to be induced and translocated to the nucleus in ocular tissue cells under hyperosmolar stress." (PMID 31766286, 2019). "Our results suggest a potential role of NFAT5 and NF-κB in the proinflammatory effect in LGs and cornea, which offers a target for new therapies to treat dry eye syndrome." (PMID 31766286, 2019). "Radiation exposure to the head and neck induced NFAT5 expression and its dependent signaling pathways in the LG, which is deeply related to radiation-induced dry eye." (PMID 31766286, 2019). "This study suggests that NFAT5 might be one of the targets in the treatment of radiation-induced dry eye syndrome." (PMID 31766286, 2019). "Therefore, our aim was to analyze and characterize in vitro conjunctival CCL2 induction in a hyperosmolar model of dry eye and to determine the relationship between NFAT5 and CCL2 on HeLa-modified conjunctiva-derived cells." (PMID 27486749, 2016). "We believe that ALA reduces the NFAT5–NK-κB axis related to inflammation in the LG after radiation and that these effects of ALA might ameliorate radiation-induced dry eye syndrome." (PMID 31766286, 2019).
Hepatic steatosis (3 papers, 2017 to 2020). Steatosis is a term used to denote lipid accumulation within hepatocytes. "Compared with wild-type diabetic mice, diabetic NFAT5+/- mice displayed decreased body weight, fat mass, hepatic steatosis, and macrophage infiltration." (PMID 33015193, 2020).
Immunodeficiency (3 papers, 2009 to 2020). Failure of the immune system to protect the body adequately from infection, due to the absence or insufficiency of some component process or substance. "Nfat5 has also a function in the immune system for the macrophage and T lymphocyte function, and haploinsufficiency is associated with immunodeficiency." (PMID 32059438, 2020).
ischemic stroke (3 papers, 2024 to 2025). A stroke disorder caused by obstruction of blood flow to the brain, due to thrombotic (local blood clot formation) or embolic (due to a blood clot or other material traveling from another site) event. "In this study, we confirmed the role of microglial NFAT5 in the acute phase of ischemic stroke and provided insights into the underlying mechanism of NFAT5 in microglia-induced neuroinflammation." (PMID 40831534, 2025). "To explore the role of microglial NFAT5 in ischemic stroke, we evaluated brain infarct volumes in mice using magnetic resonance imaging." (PMID 40831534, 2025). "Recently, we showed that hypoxia triggers the activity of NFAT5 in endothelial cells, which play a critical role in the regulation of inflammation, tissue regeneration and brain (re)perfusion after ischemic stroke." (PMID 39710754, 2024). "The cross-cohort analysis of mice subjected to experimental ischemic stroke revealed a significantly increased infarct lesion size in Nfat5(EC)−/− mice as compared to Nfat5fl/fl littermate mice." (PMID 39710754, 2024). "While both Slco4a1 and Slc6a6 are known targets of NFAT5, the latter may in fact influence the outcome of ischemic stroke by regulating the transport of the neuroprotective endogenous amino acid taurine through the BBB." (PMID 39710754, 2024). "We thus hypothesized that NFAT5 controls endothelial stress responses after ischemic stroke, which are required for tissue recovery." (PMID 39710754, 2024). "Furthermore, we propose that targeting NFAT5 may be a promising approach to prevent microglia-induced neuroinflammation and neuronal apoptosis following ischemic stroke." (PMID 40831534, 2025). "Therefore, tissue hypoxia, osmotic stress, oxidative stress and/or inflammation evolving during ischemic stroke may also activate NFAT5-dependent stress responses in brain cells upon ischemic injury." (PMID 39710754, 2024). "However, the role of microglial NFAT5 in ischemic stroke remains unclear." (PMID 40542608, 2025).
myasthenia gravis (3 papers, 2016 to 2025). Myasthenia gravis (MG) is a rare, clinically heterogeneous, autoimmune disorder of the neuromuscular junction characterized by fatigable weakness of voluntary muscles. "In myasthenia gravis (MG), tacrolimus, an immunosuppressant, reduces NFAT5 and G0S2 expression in PBMCs, providing insights into both disease mechanisms and tacrolimus' mode of action." (PMID 40421201, 2025).
oral cancer (3 papers, 2021 to 2022). "lncRNA TTN-AS1 contribute to oral cancer development by inhibition of apoptosis in OSCC cells through regulating miR-411-3p/NFAT5 axis." (PMID 35898889, 2022). "Likewise, a cell culture study revealed that the NFAT5 transcription factor is able to promote oral cancer cell proliferation via changes in the subcellular localization of the epidermal growth factor receptor." (PMID 35955417, 2022).